MYC (MYC proto-oncogene, bHLH transcription factor)
Diseases named in the same sentence as MYC in open-access papers (continued):
Sharing a sentence is not in itself a finding about the gene and the disease.
colorectal cancer (continued). "The c-MYC gene can promote tumorigenesis in various malignant tumors and mediate the critical role in the colorectal cancer (CRC) progression." (PMID 27619912, 2016). "The purpose of our research was to determine the prognostic impact and clinicopathological feature of c-MYC and β-catenin overexpression in colorectal cancer (CRC) patients." (PMID 27619912, 2016). "The aim of this study was to determine the incidence and clinicopathological significance of c-MYC gene copy-number (GCN) gain in patients with primary colorectal cancer (CRC)." (PMID 26426996, 2015). "The c-MYC expression level in surgically resected primary colorectal cancer tissues of patients with recurrence following 5-FU-based adjuvant chemotherapy was significantly higher than that of patients without recurrence (P = 0.002)." (PMID 25689483, 2015). "Our results showed that the c-MYC expression level in resected colorectal cancer tissues markedly correlated with recurrence following 5-FU-based adjuvant chemotherapy." (PMID 25689483, 2015). "Altogether, the CCAT lncRNA family is proving to be complex and important in the involvement of colorectal cancer, and possibly other cancers, and in the regulation of MYC expression." (PMID 27077133, 2015). "Nevertheless, few studies have examined the clinicopathological implications of c-MYC status in colorectal cancer (CRC)." (PMID 26426996, 2015). "Here, we identify MYC-repressed lncRNAs named MYCLo-4, -5 and -6 by comparing 3 categories of lncRNAs (downregulated in highly MYC-expressing colorectal cancer, up-regulated by MYC knockdown in HCT116, upregulated by MYC knockdown in RKO)." (PMID 26003165, 2015). "In this study, we found that the c-MYC expression level in primary colorectal cancer tissues correlated with the recurrence rate following 5-fluorouracil (5-FU)-based adjuvant chemotherapy." (PMID 25689483, 2015). "Dysregulation of MYC (HGNC:7553) is an early consequence of activating mutations in APC(HGNC:583), a key driver mutation in the adenoma-carcinoma pathway in colorectal cancer (CRC)." (PMID 24503701, 2014). "Further, SPDEF inhibited the expression of β-catenin-target genes in mouse colon tumors, and interacted with β-catenin to block its transcriptional activity in colorectal cancer cell lines, resulting in lower levels of cyclin D1 and c-MYC." (PMID 24472151, 2014). "TCF4 is known to play a role in Wnt signaling (frequently deregulated in colorectal cancer) and MYC is one of the target genes of the Wnt signaling pathway." (PMID 23752272, 2013). "The MYC oncoprotein is a master regulator of cell growth and transcriptional amplification and is aberrantly overexpressed in a broad spectrum of human cancers, including colorectal carcinoma." (PMID 42319868, 2026). "The results showed that in colorectal cancer, the expression of SLC35A2 was positively correlated with the expression of four MYC-associated genes, including MYC, Cyclin dependent kinase 4 (CDK4), Polo like kinase 1 (PLK1), and Pescadillo ribosomal biogenesis factor 1 (PES1)." (PMID 40303483, 2025). "Aberrations in MYC and NCAPG2 expression or mutations may serve as valuable biomarkers for colorectal cancer, providing insight into early detection, assessing disease severity and predicting prognosis." (PMID 38637125, 2024). "Furthermore, the researchers demonstrated that STK16 knockout or pharmacological inhibition significantly curtailed colorectal cancer proliferation and c-MYC expression in in vivo animal models." (PMID 38622518, 2024). "Furthermore, we revealed that STK16 promoted colorectal cancer progression dependent on c-MYC S452 phosphorylation." (PMID 38622518, 2024). "Targeting PVT1 could be a potential therapeutic approach for colorectal cancer patients, potentially leading to the inhibition of oncogenic MYC at both RNA and protein levels." (PMID 39830506, 2024). "Proto-oncogenic MYC is frequently dysregulated in colorectal cancer (CRC)." (PMID 39075086, 2024).
colorectal cancer (continued). "Importantly, colorectal cancer proliferation mediated by STK16 was found to be dependent on the phosphorylation of c-MYC at S452." (PMID 38622518, 2024). "Furthermore, we conducted FISH on 12 additional FFPE samples obtained from 11 colorectal cancer patients (seven males, four females), all previously identified as ecDNA+ for cargo genes MYC or ERBB2 by GCAP." (PMID 38373991, 2024). "Furthermore, we had revealed that STK16 knock-out or the pharmacological inhibition of STK16 significantly inhibited colorectal cancer proliferation and c-MYC expression in vivo." (PMID 38622518, 2024). "The inhibition of glycolytic genes in colorectal cancer cells by diclofenac might be explained by a reduction in c-MYC expression that alters STAT-3 signalling through its decreased phosphorylation." (PMID 38229111, 2024). "Furthermore, preclinical studies have revealed that Clostridium butyricum treatment of colorectal cancer cells result in MYC degradation through increased proteasome-mediated ubiquitination, thereby enhancing the anti-PD-1 immunotherapeutic efficacy." (PMID 38566102, 2024). "Besides, the proliferation of colorectal cancer mediated by STK16 depended on the phosphorylation of c-MYC at S452." (PMID 38622518, 2024). "In this study, by using robust bioinformatics and machine learning methods, we provide evidence that high CBLL1 mRNA expression is specifically associated with consensus molecular subtype 2 (CMS2) in colorectal cancer patients, which is characterised by strong activation of the WNT and MYC pathways." (PMID 38339195, 2024). "Accordingly, revealing novel post-translational modification sites of MYC might provide an effective therapeutic target for colorectal cancer patients." (PMID 37596667, 2023). "In addition, lncRNA CCAT1-L, which is transcribed specifically in human colorectal cancers, plays an important role in MYC transcriptional regulation and promotes long-range chromatin looping." (PMID 37232821, 2023). "Collectively, these findings imply that the NEK8/MYC signaling pathway might be a novel target for colorectal cancer treatment." (PMID 37596667, 2023). "Besides, we uncovered that NEK8-induced cancer cell proliferation and colorectal cancer progression depend on the serine 405 phosphorylation of MYC by in vivo or in vitro assays." (PMID 37596667, 2023). "However, colorectal cancer with c‐MYC overexpression demonstrated improved 5‐year survival compared with the c‐MYC‐negative group." (PMID 36694106, 2023). "MYC is also a key driver in cancer stem cells of breast and colorectal cancers." (PMID 37370820, 2023). "IGF2BP1 also binds to and stabilizes MYC mRNA and upregulates the MYC protein in colorectal cancer." (PMID 37686524, 2023). "In addition, MYC is marked for degradation by other ubiquitin ligases such as MAGI3 which is downregulated in poor prognosis colorectal cancer." (PMID 36969025, 2023). "However, another study discovered that the deletion of HUWE1 in an APC-based mouse model of colorectal cancer accelerates tumorigenesis by increasing the levels of MYC and DNA damage accumulation." (PMID 36831013, 2023). "Furthermore, RNA interference using these conjugated nanoparticles carrying microRNAs directed against MYC suppressed the transformed phenotype in relevant breast and colorectal cancer cell lines with an efficiency comparable to virally based systems." (PMID 36969025, 2023). "Based on these findings, we propose that the NEK8/c-MYC signaling pathway could be a potential therapeutic target for colorectal cancer." (PMID 37596667, 2023). "Our analysis identified that all eight cell lines sensitive to ZKN-157 belong to the CMS2 subtype of colorectal cancer which is characterized by high MYC and WNT signaling activation, whereas the insensitive and intermediate cell lines distributed across all four CMS subtypes." (PMID 37377612, 2023).
colorectal cancer (continued). "Although acetylation of H3K27 histone modification is typically found at the enhancers, publicly available data on the Cistrome data browser indicates that the H3K27 is acetylated at the MYC promoter in HCT-116 (colorectal carcinoma) and in A549 (lung adenocarcinoma) cells." (PMID 37190167, 2023). "A previous study suggested that MYC is among a group of genes whose epigenetic signature may be used as an early biomarker for detecting colorectal cancer." (PMID 36139061, 2022). "Interestingly, the established colorectal cancer cell line HCT116 exhibited reduced fitness in low attachment following expression of MYC S146L." (PMID 36018850, 2022). "MGA has also been reported to contribute to MYC-mediated pathway in colorectal cancer cell lines." (PMID 36249027, 2022). "Furthermore, a group found that the m6A methyltransferase METTL3 promoted the malignant proliferation of colorectal cancer cells by directly or indirectly upregulating MYC expression." (PMID 35614935, 2022). "In addition, one group recently found that FTO is regulated by miR-96, which affects the methylation level of MYC and increase the expression of MYC, thus participating in the pro-proliferative and anti-apoptotic effects of miR-96 in colorectal cancer." (PMID 35614935, 2022). "In this study, we demonstrate that the MYC 3′UTR is shortened in colorectal cancer (CRC)." (PMID 34937878, 2022). "The eRNAs inducing oncogene expression can be considered as potential therapeutic targets, as for instance CCAT1, which directly drives MYC expression in colorectal cancer or other eRNAs specifically transcribed at MYC super-enhancer in hepatocellular carcinoma." (PMID 35454885, 2022). "Depletion of LUCAT1 results in the inhibition of colorectal cancer cells proliferation and reduced MYC expression levels, thus suggesting that LUCAT1 plays a critical role in the control of MYC transcripton in colorectal cancer likely by a G4-mediated inhibition of nucleolin function." (PMID 34073075, 2021). "The enhanced activity of the critical pathways such as MYC and epithelial-mesenchymal transition may also lead to the progression of colorectal cancer." (PMID 34804112, 2021). "In colorectal cancer, the upregulated expression of MYC in cancer tissues has been well determined." (PMID 32855971, 2020). "MYC can induce apoptosis in variousdiseases such as liver and colorectal cancers." (PMID 32779435, 2020). "A recent study had demonstrated that downregulation of both SMS and MYC synergistically induces apoptin Bim expression in colorectal cancer cells, indicating that combined inhibition of SMS and MYC signaling may be an effective therapy for colorectal cancer." (PMID 33292222, 2020). "It has been reported that c-MYC inhibited the expression of LPP-AS2 in colorectal cancer." (PMID 32962742, 2020). "Since MYC activates the transcription of mitochondrial one-carbon metabolism genes, we hypothesized that MYC-driven colorectal cancers should manifest the formate-dependent metabolic switch." (PMID 32366892, 2020). "In summary, here, we present the novel colorectal cancer cell lines BKZ-2 and BKZ-3 as promising cellular in vitro models for colorectal carcinomas and identify the MYC/NMYC molecular pathway involved in CSC-induced carcinogenesis with relevant therapeutic potential." (PMID 32927768, 2020). "Interestingly, high UNR/CSDE1 expression was associated with poor prognosis and correlated positively with c-MYC expression in colorectal cancer samples and cell lines." (PMID 31027221, 2019). "Here, the authors show in a mouse model of inherited colorectal cancer that deletion of AP4 decreased the frequency of c-MYC-driven intestinal adenomas, and reveal Ap4 as a mediator of adenoma initiation and regulator of colonic and intestinal stem cell and Paneth cell homeostasis." (PMID 30177706, 2018).
colorectal cancer (continued). "The finding that MYC slightly affected CLK inhibitor‐dependent AS events was also supported by a previous finding that CLK inhibitor, T3‐dependent AS events mostly (~ 75%) overlapped between the hTERT un‐transformed fibroblast cells and MYC‐amplified HCT116 colorectal cancer cells." (PMID 29769258, 2018). "Since the overexpression of CAAT1-L activates in cis MYC transcription and promotes tumorigenesis, it has been proposed that this lncRNA contributes to the aberrant expression of c-Myc in the pathogenesis of human colorectal cancer." (PMID 29443889, 2018). "In addition, lncRNA CCAT1-L together with CTCF can mediate a 335-kb interaction between the MYC promoter and its enhancer in colorectal cancer." (PMID 29149895, 2017). "Moreover, PVT1 expression was up-regulated in colorectal cancer tissues, which correlated with the expression of MYC and many MYC regulating genes FUBP1, EZH2, and NPM1." (PMID 29108264, 2017). "Moreover, Menssen and collaborators found a positive feedback loop between SIRT1 and MYC activation in colorectal cancer." (PMID 29383100, 2017). "Specific instances of this type of effect have been observed in colorectal cancer risk loci where for example the risk SNP rs6983267 within 8q24 disrupts a chromatin regulatory network involving interactions between three genes CCAT2, CCAT1 and MYC." (PMID 28062664, 2017). "Indeed, FIR is an essential MYC repressor, as FIR knockdown is associated with MYC dysregulation ex vivo and loss-of-function FIR mutations are associated with colorectal cancer displaying increased MYC abundance." (PMID 28398229, 2017). "It has been reported that CCAT1-L (colorectal cancer specific lncRNA) localizes to its site of transcription and functions as a cis-transcriptional regulator of MYC, promoting long-range chromatin looping and interacting with the transcriptional regulator protein, CTCF15." (PMID 27572135, 2016). "Moreover, MYC gene is ranked at 9 (0.062%) among 14433 human genes for colorectal cancer resulting from a state-of-the-art disease gene prediction tool, CIPHER." (PMID 26029998, 2015). "Additionally, multiple lines of evidence have demonstrated that MYC can suppress the expression of CDKN1A in cancer like colorectal cancer." (PMID 26083494, 2015). "Furthermore, ROC curve analysis was used to obtain the optimal cut-off value of c-MYC mRNA levels in primary surgical cancer tissues of colorectal cancer patients." (PMID 25689483, 2015). "Instead, this increase could be due to an inadvertent sampling of cancerous tissue at this time-point, although the tissue obtained is from the resection margin, as it is known that colorectal carcinomas frequently have overexpression of MYC." (PMID 26371767, 2015). "Interestingly MYC over-expression as determined by Northern blot analysis was reported as a biomarker of good outcome in colorectal cancer as far back as 1996." (PMID 24503701, 2014). "Since the three pluripotent genes NANOG, OCT4, and c-MYC were hypermethylated in colorectal carcinoma HCT116 cells, we asked whether the same pattern of methylation would be observed in the rare putative CSC population in HCT116 cells." (PMID 24023739, 2013). "Additionally, some reports have shown that rs6983267 has a long range physical interaction with a promoter region of MYC in colorectal cancer cell lines." (PMID 22848671, 2012). "Interestingly, another study demonstrated that transcriptional activity of the MYC promoter was down-regulated by up-regulation of RUNX3 in colorectal cancer cells." (PMID 22028816, 2011). "DM are acentric extrachromosomal chromatin which may lead to an amplification of oncogenes, like c-MYC amplification in colorectal carcinoma." (PMID 21457541, 2011). "Furthermore, the next evidence for our prediction of c-MYC/let-7c interaction is the fact that frequent deletions in chromosome 21 (21q21) have been reported in cases of lung and colorectal carcinomas and their metastases." (PMID 17877811, 2007).
colorectal cancer (continued). "Moreover, TYMS is regulated by MYC, which affects PD-1 expression in colorectal cancer." (PMID 40642061, 2025). "FAM49B has been shown to promote proliferation and metastasis of colorectal cancer (CRC) by stabilizing MYC through phosphorylation of NEK9; however, its role in shaping the immune suppressive tumor microenvironment (TME), particularly in macrophage polarization, remains unclear." (PMID 41246334, 2025). "Additionally, according to a previous study, MYC could promote ELFN1-AS1 expression as a transcription factor in colorectal cancer." (PMID 39528458, 2024). "However, the association among MYC, NCAPG2 and colorectal cancer (CRC) is still unclear." (PMID 38637125, 2024). "Finally, pemigatinib did not result in MYC ecDNA loss in the COLO 320DM colorectal cancer cell line, which does not contain FGFR2 ecDNAs, showing that the loss of MYC ecDNAs in SNU16m1 cells is specifically due to the coupling with FGFR2 ecDNAs." (PMID 39506152, 2024). "This suggests that CCAL could increase the development of CRC by targeting and activating AP-2, that CCAT1-L plays a part in the control of MYC transcription and encourages lengthy chromatin looping, and that CCAT1-L is site-specific transcribed upstream of MYC in human colorectal cancer." (PMID 38294554, 2024). "Furthermore, the MYC gene encodes five sites with such tripeptides having the diproline (Pro-Pro) motif, and mutation of all five sites can restore MYC protein levels in DHPS-depleted HCT116 colorectal cancer cells." (PMID 39125743, 2024). "Furthermore, depletion of EIF2B5 facilitated MYC-driven apoptosis of colorectal cancer SW480 cells." (PMID 36100884, 2022). "Moreover, GSK3β reduces MZF1 expression, leading to c-MYC downregulation in colorectal carcinoma." (PMID 36499054, 2022). "Furthermore, overexpression of IGF2BP1 is found to be associated with increased c-MYC and RAS expressions, while loss of IGF2BP1 could induce caspase-3 and PARP-mediated apoptosis in colorectal cancer cell lines." (PMID 28693523, 2017). "To investigate whether c-MYC expression in surgically resected primary colorectal cancer tissues correlates with recurrence following 5-FU-based adjuvant chemotherapy, we selected 20 patients who had received 5-FU-based adjuvant chemotherapy after curative surgery." (PMID 25689483, 2015). "Although this study was limited by the small number of cases and short follow-up periods after operation, the results indicate that c-MYC expression might be an early recurrence predictive marker for colorectal cancer patients following 5-FU-based adjuvant chemotherapy." (PMID 25689483, 2015). "MYC over-expression as determined by molecular means has been reported as a favorable prognostic biomarker in colorectal carcinoma (CRC)." (PMID 24503701, 2014). "Therefore, our data suggest, that enabling c-MYC activation either through oncogenic K-Ras or B-Raf, or transcriptionally by deregulation of Wnt signalling is crucial in both, the serrated route as well as in the classical route to colorectal cancer." (PMID 23045412, 2012). "Therefore, targeting SLC35A2 and MYC may be effective approaches for treating colorectal cancer." (PMID 40303483, 2025). "For example, in colorectal cancer, CD36 promoted GPC4 ubiquitination via proteasome-dependent pathway and exerts inhibitory effects on glycolysis through the β-catenin-c-MYC signaling pathway." (PMID 40083702, 2025). "Beyond MYC, recent research has identified MIG1 as a critical coordinator of nuclear-mitochondrial communication, regulating glycolysis specifically in colorectal cancer." (PMID 40864752, 2025). "Our previous studies demonstrated that acidic environments promote the malignant phenotypes of gastric and colorectal cancer by regulating macrophage-secreted cytokines and influencing the STAT3/c-MYC axis in tumor cells." (PMID 40722682, 2025).